PRDX3 (peroxiredoxin 3)
Diseases named in the same sentence as PRDX3 in open-access papers (continued):
Sharing a sentence is not in itself a finding about the gene and the disease.
osteoarthritis (3 papers, 2021 to 2025). A noninflammatory degenerative joint disease occurring chiefly in older persons, characterized by degeneration of the articular cartilage, hypertrophy of bone at the margins and changes in the synovial membrane. "This study aims to explore the influence of PRDX3 on ferroptosis and oxidative stress of osteoarthritis cartilage injury and the possible underlying mechanism." (PMID 40757971, 2025). "Next, the SIRT3 inhibitor also promoted ferroptosis and mitochondrial damage in the in vitro osteoarthritis model with the presence of PRDX3." (PMID 40757971, 2025). "PRDX3 suppressed reactive oxygen species accumulation and mitochondria-dependent ferroptosis in the in vitro model or mice model of osteoarthritis." (PMID 40757971, 2025). "PRDX3 up-regulation reduced SIRT3 ubiquitination, and si- PRDX3 induced SIRT3 ubiquitination in the in vitro model of osteoarthritis." (PMID 40757971, 2025). "In the mice osteoarthritis model, PRDX3 up-regulation also suppressed GPX4 protein expression in the articular tissue of osteoarthritis mice." (PMID 40757971, 2025). "Meanwhile, it was discovered that in the osteoarthritis model, PRDX3 induced SIRT3 expression level by inhibiting the ubiquitination of SIRT3." (PMID 40757971, 2025). "This study was designed to investigate the impact of peroxiredoxin 3 (PRDX3) on ferroptosis and oxidative stress in osteoarthritis cartilage injury and its potential mechanism." (PMID 40757971, 2025). "Subsequently, the molecular mechanism by which METTL3 mediates ferroptosis in osteoarthritis through PRDX3 was investigated." (PMID 40757971, 2025). "Meanwhile, the SIRT3 inhibitor (10 μM of SRT AGK2) suppressed SIRT3 and GPX4 protein expressions and inhibited the effects of PRDX3 on ROS accumulation in the in vitro osteoarthritis model." (PMID 40757971, 2025). "In the in vitro osteoarthritis model, PRDX3 up-regulation led to an increase in the protein expressions of PRDX3 and SIRT3, while si-PRDX3 suppressed PRDX3 and SIRT3 protein expressions." (PMID 40757971, 2025). "Sh-PRDX3 promoted osteoarthritis cartilage injury in the mouse model via the induction of oxidative stress." (PMID 40757971, 2025). "Subsequently, single-cell analysis indicated that the PRDX3 gene was expressed in bone cells in osteoarthritis patients." (PMID 40757971, 2025). "Subsequently, the mechanism of PRDX3 was investigated in mitochondria-dependent ferroptosis in osteoarthritis using a gene chip." (PMID 40757971, 2025). "In osteoarthritis patients, the mRNA expression of PRDX3 was negatively correlated with METTL3 mRNA expression, but not with METTL14 mRNA expression." (PMID 40757971, 2025). "Targeting METTL3 or PRDX3 is thus a potentially effective therapeutic strategy for patients with osteoarthritis cartilage injury." (PMID 40757971, 2025). "In the in vitro osteoarthritis model, PRDX3 up-regulation enhanced JC-1 disaggregation and calcein-AM/CoCl2, and alleviated mitochondrial damage." (PMID 40757971, 2025). "Heat map and Gene Ontology - Biological Process (GO-BP) enrichment analysis demonstrated that PRDX3 mRNA expression was downregulated in osteoarthritis patients." (PMID 40757971, 2025). "Single-cell analysis revealed that the PRDX3 gene was expressed in bone cells of osteoarthritis patients." (PMID 40757971, 2025). "In the osteoarthritis model, PRDX3 induced SIRT3 expression to regulate ROS accumulation and mitochondria-dependent ferroptosis." (PMID 40757971, 2025). "In contrast, si-PRDX3 decreased JC-1 disaggregation and calcein-AM/CoCl2, and promoted mitochondrial damage in the in vitro model of osteoarthritis." (PMID 40757971, 2025). "In this study, the SIRT3 agonist (0.05 μM of SRT 1720 dihydrochloride) was used to induce SIRT3 and GPX4 protein expressions and attenuate the effects of si-PRDX3 on ROS accumulation in the in vitro osteoarthritis model." (PMID 40757971, 2025).
osteoarthritis (continued). "Moreover, METTL3-mediated m6A modification decreases PRDX3 mRNA stability by YTHDF1 in the osteoarthritis cartilage injury model." (PMID 40757971, 2025). "In the mice model of osteoarthritis, both PRDX3 mRNA and protein expression levels were suppressed." (PMID 40757971, 2025). "Sh-PRDX3 down-regulated SIRT3 expression in the articular tissue of osteoarthritis mice." (PMID 40757971, 2025). "However, the SIRT3 agonist reduced ferroptosis and mitochondrial damage in the in vitro osteoarthritis model with the intervention of si-PRDX3." (PMID 40757971, 2025). "Moreover, si-PRDX3 promoted the rate of dead cells rate, whereasPRDX3 upregulation reduced the rate of dead cells rate in the in vitro osteoarthritis model." (PMID 40757971, 2025). "Sh-PRDX3 elevated the arthritis score and cartilage injury (hematoxylin-eosin (HE) staining), increased the morphological changes score, hind paw edema index, and spleen index in osteoarthritis mice." (PMID 40757971, 2025). "Next, the sh-PRDX3 virus was utilized to reduce PRDX3 expression in an osteoarthritis mouse model." (PMID 40757971, 2025). "This study investigated the expression levels of PRDX3 in the osteoarthritis model." (PMID 40757971, 2025). "Subsequently, the mechanism of PRDX3 on SIRT3 in osteoarthritis was explored." (PMID 40757971, 2025). "In the osteoarthritis model, the expression of PRDX3 was downregulated." (PMID 40757971, 2025). "Furthermore, PRDX3 is involved in the entire process of cartilage injury in osteoarthritis." (PMID 40757971, 2025). "Conversely, si-PRDX3 reduced ECAR levels and increased OCR levels in the in vitro osteoarthritis model." (PMID 40757971, 2025). "Immunofluorescence results indicated that PRDX3 up-regulation induced the expression of both PRDX3 and SIRT3 in the in vitro model of osteoarthritis." (PMID 40757971, 2025). "PRDX3 up-regulation induced GPX4 protein expression and si-PRDX3 suppressed GPX4 protein expression in the in vitro osteoarthritis model." (PMID 40757971, 2025). "In this study, only PRDX3’s ability to reduce ferroptosis and oxidative stress of SW982 cells in osteoarthritis was analyzed." (PMID 40757971, 2025). "In conclusion, in the model of osteoarthritis cartilage injury, METTL3-mediated m6A modification decreases PRDX3 mRNA stability." (PMID 40757971, 2025). "Further elucidation of the role of PRDX3 and its relationship with the regulation of the SIRT3 pathway can facilitate the understanding of ROS accumulation and mitochondria-dependent ferroptosis and improve the clinical management of osteoarthritis." (PMID 40757971, 2025). "In osteoarthritis, METTL3 remarkably decreased the stability of PRDX3 mRNA." (PMID 40757971, 2025). "Moreover, PRDX3 up-regulation increased Extracellular acidification rate (ECAR) levels, while decreasing oxygen consumption rates (OCR) levels in the in vitro osteoarthritis model." (PMID 40757971, 2025). "Subsequently, PRDX3 up-regulation promoted cell growth and increased GSH activity levels, and decreased LDH activity, the proportion of Propidium Iodide (PI) positivity cells, and iron concentration in the in vitro osteoarthritis model." (PMID 40757971, 2025). "Moreover, sh-PRDX3 suppressed the protein expressions of both PRDX3 and SIRT3 in the articular tissue of osteoarthritis mice." (PMID 40757971, 2025).
renal fibrosis (3 papers, 2016 to 2024). A final common manifestation of a wide variety of chronic kidney diseases characterized by glomerulosclerosis and tubulointerstitial fibrosis. "In conclusion, these results revealed that TRIM39 induced PRDX3 degradation at lysine K73 and K149 through K48-linked ubiquitin to aggravate renal fibrosis." (PMID 38195664, 2024). "In this study, we demonstrated that mitochondria forms of Prdxs (Prdx3 and Prdx5) were decreased associated with renal fibrosis in UUO rat kidneys." (PMID 26872211, 2016). "Our results showed that mice with PRDX3 knockdown were more susceptible to UUO-induced renal fibrosis, but whether the same phenomenon occurs in mice with deletion of PRDX3 gene remains unclear." (PMID 38195664, 2024). "We found that PRDX3 ubiquitination was markedly increased in renal fibrosis models and it was significantly weakened when TRIM39 was silenced." (PMID 38195664, 2024). "In summary, we first found that TRIM39 induced the ubiquitination degradation of PRDX3 through the K48 chain, which resulted in the ROS accumulation, increased inflammatory cytokine production and renal fibrosis." (PMID 38195664, 2024). "The results showed that renal fibrosis, collagen deposition and ROS production in PRDX3 over-expressed group were less than control group." (PMID 38195664, 2024). "Future development of TRIM39 inhibitors or PRDX3 agonists will be a crucial direction for renal fibrosis therapy." (PMID 38195664, 2024). "Meanwhile, TRIM39 participated in the regulation of renal fibrosis through interacting with PRDX3 and mediating its ubiquitination." (PMID 38195664, 2024). "Our study was the first to demonstrate the expression of TRIM39 was increased in renal fibrosis, while PRDX3 was decreased." (PMID 38195664, 2024). "To further explore the relationship between TRIM39 and PRDX3 in renal fibrosis, we performed a tail-vein injection of the shPRDX3 in CKO mice and TRIM39Flox/Flox mice." (PMID 38195664, 2024). "To determine involvement of Prdxs in renal fibrosis, we analyzed the expression pattern of Prdxs isotypes (Prdx1, Prdx2, Prdx3, Prdx4, Prdx5, and Prdx6) in the cortex/outer stripe of outer medulla of UUO kidney." (PMID 26872211, 2016). "Among the isotypes, mitochondrial forms of Prdxs (Prdx3 and Prdx5) and Prdx6 were decreased with the progression of renal fibrosis." (PMID 26872211, 2016). "To further investigate whether TRIM39 regulated renal fibrosis and oxidative stress through PRDX3, we knocked down these two genes in HK-2 cells." (PMID 38195664, 2024). "Taken together, these results manifested that over-expression of PRDX3 could alleviate renal fibrosis by decreasing inflammation related factors in UUO mice." (PMID 38195664, 2024). "To further determine whether PRDX3 played a role in renal fibrosis, we observed the PRDX3 expression in human specimen." (PMID 38195664, 2024). "The regulation of PRDX3 on renal fibrosis was further investigated in HK-2 cells." (PMID 38195664, 2024). "Since the increase of ROS was a key pathological process of UUO, in this study, we investigated that whether PRDX3 regulated renal fibrosis by affecting oxidative stress." (PMID 38195664, 2024). "Furthermore, we also demonstrated that TRIM39 reduced H2O2 clearance through ubiquitination degradation of PRDX3, leading to ROS accumulation and aggravating renal fibrosis." (PMID 38195664, 2024). "Based on this result, it was reasonable to believe that mice with PRDX3 knocked out may be more vulnerable to renal fibrosis when subjected to UUO." (PMID 38195664, 2024). "Since proteasomal degradation of proteins was mostly related to ubiquitination modification, we speculated that TRIM39 might aggravate renal fibrosis by regulating ubiquitination degradation of PRDX3." (PMID 38195664, 2024). "Interestingly, the protective effect of TRIM39 knockout on UUO was reversed by down-regulation of PRDX3 expression, which indicated that TRIM39 might regulate renal fibrosis and oxidative stress in a PRDX3 manner." (PMID 38195664, 2024).
renal fibrosis (continued). "Mechanistically, we demonstrated that TRIM39 interacted with PRDX3 directly and induced ubiquitination degradation of PRDX3 at K73 and K149 through the K48 chain, which resulted in ROS accumulation and increased inflammatory cytokine generation, and further aggravated renal fibrosis." (PMID 38195664, 2024). "However, the involvement of Prdx3 and Prdx6 in renal fibrosis should be further elucidated." (PMID 26872211, 2016).
uveal melanoma (3 papers, 2020 to 2025). A melanoma derived from melanocytes of the uveal tract. "Regarding PRDX3, research suggested its association with metastasis and poor survival rates in uveal melanoma, and silencing PRDX3 has been found to inhibit liver cancer cell growth and promote invasion." (PMID 40281661, 2025). "PRDX3 has been found associated with metastasis and poor survival in uveal melanoma." (PMID 32729669, 2020). "PRDX3 overexpression has been identified in various cancers, and is negatively correlated with survival in uveal melanoma." (PMID 36230844, 2022).
age (2 papers, 2022 to 2025). A temporal measurement of the time period elapsed since an identifiable point in the life cycle of an organism. "Thus, it would be important to determine if PRDX3 overexpression in muscle and neuron further protect muscle against atrophy and NMJ impairment in age‐associated sarcopenia." (PMID 35199907, 2022). "The combined deficiency of PRDX3 and PRDX5 accelerates muscle aging by exacerbating oxidative stress and mitochondrial dysfunction, suggesting that enhancing their activity may be a promising therapeutic strategy to prevent sarcopenia and age‐related muscle degeneration." (PMID 41147088, 2025).
Alzheimer disease (2 papers, 2013 to 2025). A progressive, neurodegenerative disease characterized by loss of function and death of nerve cells in several areas of the brain leading to loss of cognitive function such as memory and language. "Both been implicated in Alzheimer's disease, with TXNRD1 showing a consistent upregulation in Alzheimer's disease, while the changes in PRDX3 were more variable." (PMID 40491829, 2025). "Furthermore, decreased PRDX3 levels have been observed in brain regions from patients suffering from Down syndrome, Parkinson's and Alzheimer's disease, suggesting both a common role for oxidative stress in different neurological disorders and a potential common approach to treatment." (PMID 23732987, 2013).
anaplastic thyroid cancer (2 papers, 2015 to 2022). "PRDX1, PRDX2, and PRDX3 expressions downregulated in papillary and anaplastic thyroid cancers, PRDX4 mRNA expression was moderately increased in anaplastic thyroid cancer tissues, and PRDX6 expression status showed similar levels as well as normal thyroid and thyroid cancers." (PMID 35571253, 2022). "PRDX1, PRDX2, and PRDX3 mRNA synthesis decreased in papillary and anaplastic thyroid cancers, PRDX4 mRNA expression was moderately increased in anaplastic thyroid cancer tissues, and PRDX6 expression status was at similar levels in normal thyroid and thyroid cancers." (PMID 26664298, 2015).
Atrophy (2 papers, 2023 to 2025). Any weakening or degeneration, especially through lack of use. "A case report following the original discovery study described an affected individual with a homozygous nonsense variant in PRDX3 who showed global developmental delay, cerebellar atrophy, hypotonia, speech issues, dystonia, and profound hearing impairment." (PMID 41191133, 2025).
Cerebellar atrophy (2 papers, 2023 to 2024). Cerebellar atrophy is defined as a cerebellum with initially normal structures, in a posterior fossa with normal size, which displays enlarged fissures (interfolial spaces) in comparison to the foliae secondary to loss of tissue. "The presence of cerebellar atrophy is a ubiquitous feature in patients with bi‐allelic PRDX3 mutations." (PMID 37553803, 2023). "In conclusion, a novel mutation in PRDX3 is here reported as the genetic cause of SCAR32, a disorder whose red flags seem to include cerebellar atrophy, delayed neurodevelopment, and impaired oculomotor function." (PMID 38837640, 2024).
clear-cell renal cell carcinoma (2 papers, 2019 to 2026). "We further validated the biological function role of PRDX3 in kidney clear cell carcinoma (KIRC) through reverse transcription quantitative polymerase chain reaction, Western blotting, Transwell assays, and scratch assays." (PMID 41838687, 2026).
Fanconi anaemia (2 papers, 2014 to 2024). "In other disorders with common DNA pathway defects such as in Fanconi anemia, PRDX3 was found to be downregulated in cellular models which is in line with our findings." (PMID 39611850, 2024). "Prdx4 was downregulated in acute promyelocytic leukemia and Prdx3 overoxidization was reported in ageing; moreover, Prdx3 was found to be downregulated in cells from Fanconi anaemia (FA-G)." (PMID 24876913, 2014).
gastric cancer (2 papers, 2022 to 2025). A primary or metastatic malignant neoplasm involving the stomach. "For example, anti-silencing function 1B (ASF1B), a highly conserved histone chaperone protein, was found to interact with the transcription factor FOXM1 in gastric cancer cells, resulting in the increased enrichment of FOXM1 in PRDX3 promoter for PRDX3 transcription." (PMID 40227215, 2025).
hypothyroidism (2 papers, 2013 to 2024). Abnormally low levels of thyroid hormone. "LRRK2 deficiency can also be directly linked, via PRDX3, to the potential dysregulation of iodothyronine deiodinase, type III (DIO3), plausibly leading to hypothyroidism via conversion of T4 and T3 to inactive derivatives." (PMID 23799078, 2013).
kidney cancer (2 papers, 2011 to 2021). Primary or metastatic malignant neoplasm involving the kidney. "This is in agreement with an earlier study where the authors found that only 23% of kidney cancer revealed positive immunoreactivity for PRDX3." (PMID 21760917, 2011). "Considering this and the apparent mitochondrial alterations in kidney cancer we selected for further validation two mitochondrial proteins (prohibitin, PRDX3) which we found as differentially expressed in our 2D-DIGE approach, and the S100-A9 protein." (PMID 21760917, 2011). "Increased or decreased levels of PRDXs mRNA expression levels were found among 33 tumor types, such as PRDX1, PRDX2, PRDX4 and PRDX5 increased in several cancer types, while PRDX3 and PRDX6 decreased in there types of kidney cancer (KIRP, KIRC and KICH)." (PMID 34246267, 2021). "Notably, when compared to adjacent or normal tissues, PRDX1, PRDX2, PRDX4 and PRDX5 were significantly up-regulated expression in several cancer types (UCEC, READ, BLCA, BRCA, CHOL, COAD, LIHC, THCA), while PRDX3 and PRDX6 were down-regulated expression in kidney cancers." (PMID 34246267, 2021).
laryngeal carcinoma (2 papers, 2014 to 2017). Carcinoma that arises from the laryngeal epithelium. "Knockdown of PRDX3 in the Hep-2 laryngeal carcinoma epithelial cell line significantly enhanced Hep-2 cells’ apoptosis and inhibited their proliferation and migration." (PMID 27966448, 2017). "Compared with si-NC, Hep-2 cells with knockdown of PRDX3 migrated slower, suggesting that knockdown of PRDX3 inhibited the migration ability of laryngeal cancer Hep-2 cells." (PMID 27966448, 2017).
nasopharyngeal carcinoma (2 papers, 2017 to 2020). A carcinoma arising from the nasopharyngeal epithelium. "Besides, serum proteomics-based analysis identified autoantibodies against PRDX3 as potential diagnostic biomarkers in nasopharyngeal carcinoma." (PMID 32382548, 2020).
prostate adenocarcinoma (2 papers, 2017 to 2023). "The GEPIA platform was used to measure the correlation between the antioxidant protein expression: Superoxide Dismutase 1 and 2 (SOD1 and SOD2) and peroxiredoxin 3 (PRDX3) with the NEK6 gene expression in prostate adenocarcinoma samples." (PMID 36672191, 2023). "It was reported that levels of PRDX3 protein are higher in prostate tumor tissues than in their adjacent normal prostate tissues or disease-free normal prostate tissues, suggesting a potential role of PRDX3 in prostate adenocarcinomas." (PMID 29113303, 2017).